MLANA (melan-A)
Diseases named in the same sentence as MLANA in open-access papers (continued):
Sharing a sentence is not in itself a finding about the gene and the disease.
amelanotic melanoma (7 papers, 2020 to 2025). A melanoma characterized by the complete absence of melanin pigment in the melanoma cells. "The diagnosis of amelanotic melanoma was supported by the combined immunohistochemical positivity for S-100, Melan-A, and HMB-45, confirming melanocytic origin despite the absence of visible pigmentation." (PMID 41536409, 2025). "Histopathology confirmed amelanotic melanoma, supported by immunopositivity for S-100, Melan-A, and HMB-45." (PMID 41536409, 2025). "The percentages of Melan-A-positive cells in A-375 amelanotic melanoma, CCD-1064Sk fibroblast and HaCaT keratinocyte cell lines were not higher than 6%." (PMID 34944864, 2021). "Histopathological analysis of a cervical lymph node biopsy confirmed metastatic epithelioid amelanotic melanoma, with immunohistochemistry demonstrating positive staining for S100, Melan-A, and CDX10, while cytokeratin AE1/AE3 was negative." (PMID 40837908, 2025). "If Melan-A ICC is negative and amelanotic melanoma is still strongly suspected, histopathology is recommended." (PMID 35448673, 2022). "Melanocytic markers such as HMB45 and Melan-A are negative in EMPNST and this fact helps to rule out its closest differential diagnosis of amelanotic melanoma." (PMID 33520482, 2020).
adrenocortical adenoma (5 papers, 2016 to 2024). "The immunohistochemical profile (alpha-inhibin+, Melan-A+, synaptophysin+) indicated the adrenocortical origin of the tumor, diagnosed as ectopic adrenocortical adenoma." (PMID 27094262, 2016).
breast carcinoma (5 papers, 2013 to 2024). "In the present study, MDA-MB-435 cells growing in dense cultures were found to exhibit lower expression of the breast cancer marker, mammaglobin and higher expression of the melanocyte markers, Melan A and S100." (PMID 23599796, 2013). "Additionally, the B16F0-Dicer cells had similar Dicer protein expression compared to normal mouse melanocytes (Melan A) and the low Dicer expressing breast cancer cell line 4T1." (PMID 27356752, 2016). "Cell density was observed to correlate with differentiation status in breast cancer and is consistent with the hypothesis that Melan A is a suitable marker for differentiation in breast cancer." (PMID 23599796, 2013). "Furthermore, for the first time, cell density was demonstrated to correlate with differentiation state in breast cancer and additional evidence that Melan A is a suitable marker for differentiation in breast cancer is provided." (PMID 23599796, 2013). "Melan-A and HMB45 are useful because they are more specific, but staining is sometimes focal and they are occasionally expressed by breast cancer." (PMID 38910784, 2024). "Further studies using protein expression analyses clearly demonstrated that two MDA-MB-435 sublines (termed MDA-MB-435S and -HGF) expressed the melanocytic genes melan A and tyrosinase, but not typical breast cancer genes, mammaglobin, prolactin and pS2." (PMID 23599796, 2013). "In the present study the three breast cancer cell lines, MCF-7, MDA-MB-231 and MDA-MB-435, were systematically analyzed for mRNA and protein expression of major epithelial (cytokeratin isoforms), mammary (mammaglobin) and melanocytic (melan A and S100-protein) markers." (PMID 23599796, 2013).
melanocytic neoplasm (5 papers, 2015 to 2025). "HMB-45, MART-1 (Melan A), S-100, and tyrosinase are almost always diffusely positive in primary melanocytic neoplasms of the CNS." (PMID 26294993, 2015). "These include Melan-A, HMB-45, tyrosinase, and MITF, which are typically specific to melanocytic neoplasms." (PMID 40598734, 2025). "An immunohistochemical cocktail that contains antibodies against Melan-A, PNL-2, TRP-1, and TRP-2 is the current gold standard to identify melanocytic neoplasms." (PMID 35448673, 2022). "Immunocytochemistry (ICC) for Melan-A may be helpful to differentiate between these non-melanocytic tumors or to diagnose amelanotic melanocytic neoplasms." (PMID 35448673, 2022).
melanoma in situ (5 papers, 2017 to 2025). "Melan-A can aid in the identification of isolated tumoral melanocytes located in the dermis, which can upstage a previously diagnosed melanoma in situ with HE to an invasive lesion." (PMID 36980327, 2023). "Melanoma in situ was negative for GATA3 but positive for S100, melan-A and HMB45 whereas EMPD had an opposite immunoprofile." (PMID 28693610, 2017).
paraganglioma (5 papers, 2008 to 2022). A benign or malignant neoplasm arising from paraganglia located along the sympathetic or parasympathetic nerves. "Paragangliomas are negative to keratin and melan-A, whereas the tumor in the present case was positive for these markers." (PMID 22008415, 2011). "The tumor cells of paraganglioma are usually negative for melanocytic markers, such as Melan-A, HMB-45, and MITF." (PMID 18638402, 2008).
rhabdomyosarcoma (5 papers, 2010 to 2024). A rare aggressive malignant mesenchymal neoplasm arising from skeletal muscle. "Mixed germ cell tumor, most often metastasis from testicular primary, with somatic teratomatous malignancy (rhabdomyosarcoma) can be excluded by positive staining of PLAP and cytokeratins and negative staining of vimentin, Melan-A and calretinin." (PMID 20687934, 2010).
angiosarcoma (4 papers, 2018 to 2025). A malignant tumor arising from the endothelial cells of the blood vessels. "However, in this case the angiosarcoma cells expressed neither Melan-A nor HMB45, and the immunoprofile of angiosarcoma clearly differed from that of renal AML." (PMID 30111336, 2018). "The tumor cells were negative for desmin, HHF35, HMB45, Melan A, MITF, c-kit, DOG1, cytokeratin AE1/AE3, h-caldesmon, STAT6, CD68, CD31, Factor 8, and ERG, making diagnoses of PEComa, GIST, SFT, and angiosarcoma unlikely." (PMID 34797454, 2021).
influenza (4 papers, 2008 to 2022). An acute viral infection of the respiratory tract, occurring in isolated cases, in epidemics, or in pandemics; it is caused by serologically different strains of viruses (influenzaviruses) designated A, B, and C, has a 3-day incubation period, and usually lasts for 3 to 10 days. "Treatment with an anti-PD-1 antibody was shown to increase NY-ESO-1-specific CD8+ T cells expansion in melanoma patients and in contrast to EBV, influenza, or Melan-A/MART-1-specific CD8+ T cells, NY-ESO-1-specific CD8+ T cells uniquely express the PD-1 molecule." (PMID 30108590, 2018). "Total pre-and post-vaccination PBMC were tested for release of IFN-γ in ELISpot after 24 hs incubation with autologous DCs pulsed with gp100 or Melan A/MART-1 peptides and, as a control, influenza (flu58–66) peptides." (PMID 18221542, 2008).
neurofibroma (4 papers, 2009 to 2025). An intraneural or extraneural neoplasm arising from nerve tissues and neural sheaths. "Neurotized nevi demonstrated strong and diffuse positivity, in contrast to neurofibromas, whichare usually Melan-A-negative." (PMID 40507250, 2025).
nevus (4 papers, 2021 to 2022). Nevus (or naevus, plural nevi or naevi, from nævus, Latin for "birthmark") is the medical term for sharply circumscribed[1] and chronic lesions of the skin or mucosa. "As an earlier Melan-A staining indicated a > 95% nevus cell purity of the macrodissected tissue, it turns out that a subpopulation of the nevus cells was mutated." (PMID 33588787, 2021). "Subsequently, the expression of S100, Ki-67, Melan A and HMB45 and different expressions between verrucous and non-verrucous divided nevus of the eyelids were analyzed." (PMID 36057574, 2022). "To date, the expression difference of Ki-67, S100, Melan A and HMB45 has not been detected in divided nevus." (PMID 36057574, 2022).
skin tumor (4 papers, 2018 to 2024). "The authors observed loss of Melan A in brain tumor melanoma tissue compared to primary skin tumor." (PMID 30858407, 2019). "These antibodies are essential for identifying various skin tumors and include markers such as S-100, HMB-45, Melan-A, Cytokeratin 5/6, and Ber-EP4." (PMID 39061614, 2024).
adrenal tumor (3 papers, 2013 to 2021). "A panel of markers (CD56, vimentin, melan-A, inhibin-α, synaptophysin, chromogranin and SF-1) are used to establish the origin of adrenal tumors." (PMID 34803919, 2021). "In adrenal tumor, slight positivity of Melan-A was observed, but the intensity of staining was clearly weak compared with that in normal adrenal glands." (PMID 31696344, 2019). "Slight positivity of Melan-A is observed in the adrenal tumor, but the intensity of staining was clearly weak compared with those in normal adrenal glands." (PMID 31696344, 2019). "In terms of adrenal carcinoma markers vimentin and Melan-A, vimentin was negative in the HCC and adrenal tumor, and Melan-A was negative in the HCC." (PMID 31696344, 2019). "Vimentin was negative for the HCC and adrenal tumor, and Melan-A was also negative for the HCC." (PMID 31696344, 2019). "In our case, melan-A and inhibin were positive, but thyroglobulin and TTF-1 were negative, in the patient’s adrenal gland tumor." (PMID 23889916, 2013).
cyst (3 papers, 2007 to 2025). A sac-like closed membranous structure that may be empty or contain fluid or amorphous material. "The cyst-lining epithelium expresses PAX8, PAX2, and CK7, while the subepithelial stromal region shows strong positive staining for ER, PR, CD10, Melan-A, and HMB45." (PMID 41426332, 2025). "The cyst lining was positive for pancytokeratin, but negative for HMB-45, Melan-A, ER, PR, and CD10." (PMID 17376246, 2007). "The cyst lining was positive for epithelial markers (pancytokeratin, AE1-AE3, and CK7), but negative for melanocytic (HMB-45 and Melan-A), muscular (smooth muscle actin and desmin), and hormonal (ER and PR) markers." (PMID 17376246, 2007).
desmoplastic melanoma (3 papers, 2010 to 2023). A melanoma of the skin characterized by a proliferation of atypical spindled melanocytes in the dermis, in a background of abundant collagen. "The dermal component of desmoplastic melanoma is usually negative for Melan A (or Mart1) and HMB45." (PMID 20936153, 2010).
dysplastic nevi (3 papers, 2012 to 2025). "Markers, such as Melan-A, HMB-45, SOX-10, and PRAME, assist the dermopathologist on a daily basis in the differential diagnosis between severe dysplastic nevus and MIS." (PMID 36975387, 2023). "In contrast, the dysplastic nevi showing PRAME 4+ expression (n = 1) preserved p16 expression, demonstrated a low Ki-67 index (<5%), and exhibited the typical immunoprofile of benign melanocytic lesions (S-100, Melan-A positive)." (PMID 41153267, 2025). "However, melanocytic lesions including dysplastic nevi also stain positive for S100, MART-1/Melan-A and HMB-45." (PMID 23028750, 2012).
latent infection (3 papers, 2013 to 2018). "kLANA rescued mLANA deficiency, with chimeric virus establishing latent infection in vivo." (PMID 28910389, 2017). "Further, kLANA rescued mLANA deficient MHV68, allowing chimeric virus to establish latent infection in vivo." (PMID 28910389, 2017). "Further, kLANA rescued mLANA deficient MHV68, enabling a chimeric virus to establish latent infection in vivo in germinal center B cells." (PMID 28910389, 2017). "Further, mLANA K224A/K228A/K229A bound BRD4 normally, yet vmLANAK224A/K228A/K229A was deficient for latent infection." (PMID 24146618, 2013). "To define the relationship between mLANA expression in B cells and acute and latent infection, we evaluated O73.loxP and WT MHV68 infection in mice that express Cre recombinase under the control of the B cell-specific CD19 promoter [CD19Cre/+] allowing deletion of floxed ORF73 in B cells." (PMID 29364981, 2018). "Further, we found that a chimeric MHV68, expressing kLANA, but not mLANA, was capable of establishing latent infection in splenic GC B cells, thus providing a model for kLANA investigation in vivo." (PMID 28910389, 2017). "That conclusion is based on the result that BRD4 binding was reduced for mLANA K251E/K253E, however vmLANAK251E/K253E showed no latent infection phenotype." (PMID 24146618, 2013).
mesenchymal tumors (3 papers, 2004 to 2023). "Histopathologic findings on sonographic biopsy of the lesion revealed a mesenchymal tumor with positivity for melanocytic markers Human Melanin Black-45 (HMB45) and Melan-A consistent with a PEComa." (PMID 36964879, 2023). "Zamecnik and Michal found immunoreactivity for HMB-45 in four distinctively hyalinized epithelioid mesenchymal tumors of the uterus, but all four cases were negative for the other three melanogenesis markers tested (Melan-A, tyrosinase and micropthalmia transcription factor)." (PMID 15494070, 2004).
sarcoma (3 papers, 2007 to 2021). A usually aggressive malignant neoplasm of the soft tissue or bone. "The case herein presented was strong and diffusely positive with at least two melanocytic markers (HMB45 and Melan-A), which is not a finding in other sarcomas." (PMID 18053181, 2007).
spindle-cell malignant melanoma (3 papers, 2021 to 2026). "Histopathological examination showed spindle-cell malignant melanoma with diffuse Melan-A and vimentin expression and focal S100 positivity, while epithelial markers were negative." (PMID 41694883, 2026). "With the negativity of SOX10, Melan A, and HMB45, it does not support desmoplastic/spindle cell melanoma." (PMID 34940081, 2021).
viral infection (3 papers, 2012 to 2018). "Ultimately, we do not yet have a sufficiently detailed understanding of transcription in this region of the viral genome to appropriately model how mLANA regulation of latency and lytic cycle-associated gene expression impact virus infection." (PMID 22969427, 2012). "Consistent with our observation that mLANA can repress transcription arising from the TR, it is important to note that the presence of mLANA causes a downregulation of ORF73 transcript levels during virus infection in permissive fibroblasts, as detected by RT-PCR of the ORF73 coding exon." (PMID 22969427, 2012). "Co-immunoprecipitation experiments also showed that mLANA and Myc exist in the same heteromolecular complex in a context of virus infection." (PMID 23950719, 2013). "Since mLANA is a multifunctional viral protein that facilitates both lytic replication and latency establishment, we utilized this new reagent to better define mLANA’s functions in specific cell types and at certain stages of viral infection." (PMID 29364981, 2018).
Adrenocortical Tumors (2 papers, 2022 to 2024). "The negative staining for chromogranin A (CgA) ruled out pheochromocytoma, while the absence of melan-A, inhibin, and calretinin excluded adrenocortical tumors." (PMID 39493270, 2024).
cancer testis (2 papers, 2015 to 2022). "Indeed, most TA antigens, such as cancer testis antigens (e.g., NY-ESO-1 and MAGEs) and differentiation antigens (e.g., Melan-A/MART-1, gp100, and tyrosinase), are expressed in the thymus." (PMID 26635796, 2015).
clear cell renal cell carcinomas (2 papers, 2013 to 2023). "Cathepsin K, HMB-45, and Melan-A can help in distinguishing renal epithelioid-AMLs from clear cell renal cell carcinomas." (PMID 36740682, 2023). "In addition, PEComa is readily differentiated from epithelioid extra-GIST and metastatic clear-cell renal cell carcinoma by positive immunohistochemical staining for Melan-A and HMB-45 and negative staining for both CD117, Dog-1, CD34 and pan-cytokeratin (AE1/AE3)." (PMID 23587410, 2013).
ependymoma (2 papers, 2020 to 2023). A WHO grade II, slow growing tumor of children and young adults, usually located intraventricularly. "Involvement of MLANA in the regulation of NF-kappaB signaling pathway drives specific immuno-phenotype in group A ependymoma." (PMID 32266223, 2020).
Ewing sarcoma (2 papers, 2022). A small round cell tumor that lacks morphologic, immunohistochemical, and electron microscopic evidence of neuroectodermal differentiation. "The tumour cells were immunopositive for HMB45 and immunonegative for Melan A. Therefore, the EWSR1 rearrangement detected earlier was related to CCS rather than Ewing’s sarcoma/PNET." (PMID 36405939, 2022).
glioma (2 papers, 2014 to 2020). A benign or malignant brain and spinal cord tumor that arises from glial cells (astrocytes, oligodendrocytes, ependymal cells). "Intra-cytoplasmic antibody staining showed that all of the tested iHsp90 increased expression of the melanocyte differentiation antigens Melan-A/MART-1, gp100, and TRP-2, as well as MHC Class I. The gliomas showed enhanced gp100 and MHC staining." (PMID 25503774, 2014).
leiomyosarcoma (2 papers, 2015 to 2023). An uncommon, aggressive malignant smooth muscle neoplasm, usually occurring in post-menopausal women. "In addition, leiomyosarcoma usually does not express antibodies to melanosomal proteins, such as S-100 or melan-A." (PMID 26698563, 2015).
metastatic disease (2 papers, 2017 to 2023). "None of the 74 cases identified as in situ lesions using both staining techniques developed distant metastasis, but two cases identified as invasive only using Melan-A were associated with metastatic disease." (PMID 36980327, 2023).
adrenal carcinoma (1 paper, 2019). A carcinoma involving a adrenal gland. "In HE staining, the morphology of two tumors were slightly different; therefore, we evaluated two HCC markers (GPC3 and AFP) and two adrenal carcinoma markers (vimentin and Melan-A) via IHC staining." (PMID 31696344, 2019). "In adrenal carcinoma, GPC3 is not expressed, and the positivity rates of vimentin and Melan-A were 54% and 84%, respectively." (PMID 31696344, 2019).
basal cell carcinoma (1 paper, 2024). A carcinoma involving the basal cells. "The hypothesis of this study centered on exploring the potential correlations between dermatoscopic features and the expression of specific immunohistochemical markers (CD34, CD31, Melan A, and D2-40) in Basal Cell Carcinoma (BCC)." (PMID 39399171, 2024).
central nervous system melanoma (1 paper, 2025). "In addition to imaging, pathology plays a crucial role as a diagnostic tool, with markers like Melan A and HMB-45, along with the NRAS mutation, being the predominant markers identified in primary central nervous system melanoma." (PMID 40417324, 2025).
choroidal melanoma (1 paper, 2015). Malignant tumor of melanocytes of the choroid. "Melan-A has a sensitivity similar to HMB-45 in choroidal melanomas." (PMID 26316887, 2015).
endometrial stromal sarcomas (1 paper, 2022). "HMB45 and Melan A expression has been demonstrated in endometrial stromal sarcomas." (PMID 36057574, 2022).
eye tumour (1 paper, 2017). "The eye tumour shared many characteristics with the tail tumours and was diagnosed as invasive melanoma; H&E staining revealed spindle cell morphology, Melan-A and phospho-histone H3 were positive and S100 and HMB-45 were negative." (PMID 28806732, 2017).
eyelid nevus (1 paper, 2022). "This study analyzed the differential expression of Ki-67, S100, Melan A and HMB45 and identified the correlation between the clinical and histopathological features of verrucous and non-verrucous divided eyelid nevus." (PMID 36057574, 2022).
granulosa cell tumor (1 paper, 2025). A slow-growing, malignant tumor, characterize by the presence of granulosa-like cells and Call-Exner bodies, that is almost always found in the ovary. "AE1/AE3 was used to exclude an epithelial neoplasm, while inhibin and melan-A were employed to rule out sex cord stromal tumors, such as granulosa cell tumors." (PMID 41199837, 2025).